CLPP (caseinolytic mitochondrial matrix peptidase proteolytic subunit)
Diseases named in the same sentence as CLPP in open-access papers (continued):
Sharing a sentence is not in itself a finding about the gene and the disease.
cancer (continued). "Given that HSP60 and ClpP per se are likely important for the survival and functions of not only cancer cells but also normal cells, strategies or drugs that target their expression levels may have unwanted cytotoxicities in the clinic." (PMID 35653190, 2022). "Given the significance of ClpP-ATPase complexes in cellular health and survival in bacterial pathogenesis and in cancer, a fuller understanding of their structure, function, and behavior will be beneficial to current drug development efforts that target this proteolytic complex." (PMID 35245501, 2022). "Thus, dysregulation of mitochondrial homeostasis by ClpP agonists is considered a novel strategy for cancer treatment." (PMID 36388465, 2022). "The ClpP agonists inhibited CSC function in vitro and in vivo, suggesting that ClpP agonists may be effective in preventing metastasis and further studies are required to examine the efficacy of ClpP agonists on CSCs using cancer metastasis or adjuvant models." (PMID 36388465, 2022). "There lactone-based inhibitors, originally developed to target S. aureus ClpP (SaClpP), could be successfully employed to inhibit the growth of cancer cells in a ClpP-dependent manner." (PMID 34045646, 2021). "Furthermore, co-expression of both proteins at high levels in multiple tumor types was associated with shortened patient survival, strongly supporting a functional link between LONP1 and ClpP in human cancer." (PMID 33637676, 2021). "Interestingly, small modulators of ClpP activity, both activators and inhibitors, are able to impair oxidative phosphorylation in cancer cells and to induce apoptosis." (PMID 34207660, 2021). "Many studies demonstrated an increased expression of ClpP in different human cancers." (PMID 34207660, 2021). "Inhibition of LONP1 and ClpP separately reduces cancer growth and viability." (PMID 33637676, 2021). "The aim of this review is to highlight the role of ClpP in regulating mitochondrial quality control, in promoting cell proliferation and cisplatin resistance, and as a new prognostic marker and therapeutic target in human cancer." (PMID 34207660, 2021). "Despite functional similarities between LONP1 and ClpP in cancer, their regulatory mechanisms are largely unknown." (PMID 33637676, 2021). "In addition, efficient anti-cancer drug and cancer apoptosis can be achieved through targeting the mitochondrial stress response components like ClpP, proteases, and chaperones." (PMID 34717757, 2021). "We found that LONP1 and ClpP cooperate to maintain protein quality and the activity of target substrates, which may support cancer cell proliferation and survival from cellular stress." (PMID 33637676, 2021). "Most recently it could be shown that the concept of induced cell death by overactivation of ClpP can be translated from bacteria to cancer cells." (PMID 34045646, 2021). "Indeed, the ClpP activator imipridone ONC201 has shown efficacy as a single agent or in combination with other anti-cancer therapies in several solid and hematologic tumors and it is currently being tested in clinical trials." (PMID 34888254, 2021). "There is increasing evidence that LONP1 and ClpP are involved in cancer." (PMID 33637676, 2021). "ClpP, maintaining the integrity of the oxidative phosphorylation system, could represent a new potential therapeutic target for the treatment of cancer." (PMID 34207660, 2021). "Cancer cells appear to be more reliant on CLPP activity than normal cells." (PMID 32094149, 2020). "Chemical activation of CLPP is also cytotoxic in cancer cells." (PMID 32761807, 2020). "Whether ClpP inhibition or ClpP hyperactivation is a more efficient strategy to target cancer cells is a critical question which needs to be answered in future studies." (PMID 33037181, 2020).
cancer (continued). "The anti-cancer activity of imipridones is linked to different mechanisms such as inactivation of Akt and ERK, activation of mitochondrial caseinolytic protease P (ClpP), protein quality control of the endoplasmic reticulum, the cellular stress response, apoptosis and cell-cycle arrest." (PMID 33007949, 2020). "Therefore, overexpression of ClpP and other mitochondrial proteolytic machines, such as heat shock protein-90 (Hsp90), in various types of cancer is consistent." (PMID 31067645, 2019). "Meanwhile, it could be observed that CLPP/VSVMP mRNA complex showed comparable anti-cancer ability with liposome delivered VSVMP plasmid group (0.2 ± 0.1 g)." (PMID 35539419, 2018). "The anti-cancer ability of CLPP delivered VSVMP mRNA was studied in vitro." (PMID 35539419, 2018). "Alternatively, these differences may reflect cancer type–specific effects of ClpP activation." (PMID 41333384, 2025). "Thus, targeting ClpP to increase the drug sensitivity is beneficial for cancer treatment." (PMID 39261452, 2024). "In addition, it remains unclear about the tumor biology as well as underlying mechanisms for this metabolic vulnerability for LUSC cancers as the best candidate for certain ClpP activator, such as ZK53." (PMID 37923710, 2023). "ONC201 is a promising first-in-class small molecule that has been reported to have anti-neoplastic activity in various types of cancer through activation of tumor necrosis factor-related apoptosis-inducing ligand (TRAIL) as well as activation of mitochondrial caseinolytic protease P (ClpP)." (PMID 35372029, 2022). "Finally, a role of CLPP in a number of cancers is suggested by an altered abundance of ClpP transcripts in different human cancer tissues, which may result from altered metabolic states in cancer cells." (PMID 28449241, 2017). "ClpP activators ONC201 and related small molecules (TR compounds, Madera Therapeutics), have demonstrated significant anti-cancer potential in vitro and in vivo studies, including clinical trials for refractory solid tumors." (PMID 37063293, 2023). "Based on the scaffold of ONC201, ClpP activators such as 16z, TR-107 and IMP075 with enhanced enzymatic and anti-proliferative activity in cancer cells were developed." (PMID 37923710, 2023). "ClpP agonists and POLRMT inhibitors have been shown to impair cellular proliferation in multiple cancer cell lines and models." (PMID 37371693, 2023). "Both ClpP agonists and POLRMT inhibitors have intriguing anti-cancer properties that will continue to be investigated as these compounds advance in clinical trials." (PMID 37371693, 2023). "Though ClpP agonists and POLRMT inhibitors effectively reduce cancer cell proliferation, much remains to be discovered about the mechanism of action of these compounds." (PMID 37371693, 2023). "Both ClpP agonists and POLRMT inhibitors induce major metabolic alterations in cancer cells, most prominently observed with the inhibition of OXPHOS." (PMID 37371693, 2023). "Subsequently, hyperactivated ClpP accelerates the degradation of ETC substrates to interfere with mitochondrial structure and function, thus killing cancer cells." (PMID 35180892, 2022). "Multiple studies have demonstrated that ClpP and LONP1 levels are markedly increased in numerous cancers." (PMID 35180892, 2022). "Accordingly, targeting ClpP and LONP1 is anticipated to reveal a new therapeutic perspective for cancer due to the oncogenic functions of these proteins." (PMID 35180892, 2022). "Cancer cells utilize signaling molecules and transcriptional products in the UPRmt, such as ATF5, HSP60 and ClpP, to promote their proliferation, growth, invasion and metastasis." (PMID 35180892, 2022). "In fact, ClpP and LONP1 coordinately regulate mitochondrial bioenergetics in cancer, which is reflected in the observation that ClpP and LONP1 have many common substrates." (PMID 35180892, 2022).
cancer (continued). "The following sections will discuss the known cancer-specific roles of ATF5 and key UPRmt proteins downstream of ATF5: HSP60, HSP10, mtHSP70, LONP1, and ClpP." (PMID 35864539, 2022). "Although both compound classes act by the same mechanism and target the same binding site at ClpP, ADEP is particularly potent in bacteria, whereas the imipridones, from all of what is published to date, clearly surpass ADEP in cancer cells." (PMID 34109219, 2021). "Considering the pro-survival roles of LONP1 and ClpP, we next evaluated LONP1- and ClpP-mediated mitochondrial protease requirements for cancer cell adaptation to metabolic stressors, such as starvation and oxidative stress." (PMID 33637676, 2021). "As for the inhibition, hyperactivation of ClpP also impairs OXPHOS and induces cancer cell death by uncontrolled degradation of ClpP respiratory chain substrates." (PMID 34888254, 2021). "Consistent with an increased sensitivity to cellular stress after LONP1 and ClpP knockdown, we observed that inhibition of SHMT2 enhanced cancer cell sensitivity to stressors such as oxidative stress (H2O2) or starvation (low glucose)." (PMID 33637676, 2021). "This review provides an overview of the role of ClpP in regulating mitochondrial functionality, in supporting tumor cell proliferation and cisplatin resistance; finally, we discuss whether this protease could represent a new prognostic marker and therapeutic target for the treatment of cancer." (PMID 34207660, 2021). "Consistent with the cellular effects of LONP1 and ClpP inhibition, depletion of SHMT also reduced cancer cell growth and survival under cytotoxic stress conditions." (PMID 33637676, 2021). "Hence, ClpP could be exploited as a novel target in cancer treatment." (PMID 32195060, 2020). "ONC206, a second-generation imipridone, has been shown to exhibit potent anti-cancer activity through multiple mechanisms, including the antagonism of dopamine receptor D2 (DRD2), CLpP agonism, and TRAIL activation, disrupting mitochondrial protein homeostasis and inducing cellular stress responses." (PMID 40699850, 2025). "Taken together, our findings identify ClpP as a novel target for ferroptosis and suggest that ZK53 may serve as a promising candidate for enhancing ferroptosis-based cancer therapy." (PMID 41357605, 2025). "Like ClpP, ClpX expression is not prognostic in any analyzed cancer type, reinforcing its role as a conserved component of mitochondrial proteostasis." (PMID 41155556, 2025). "Importantly, both ClpP agonists and POLRMT inhibitors are reported to inhibit cancer cell proliferation with minimal effects on normal cells." (PMID 37371693, 2023). "Studies have shown that OXPHOS is also inhibited after ClpP activation in cancer cell lines, but have not determined the direct cause of inhibition." (PMID 37371693, 2023). "Activation of ClpP in multiple cancer cell models leads to non-specific degradation of mitochondrial proteins, including OXPHOS subunits." (PMID 37063293, 2023). "A survey of multiple studies indicates that ClpP agonists and POLRMT inhibitors may be differentially effective against different cancer types." (PMID 37371693, 2023). "ClpP agonists and POLRMT inhibitors are promising new anti-cancer therapeutic strategies that may act through interrupting this important cellular function." (PMID 37371693, 2023). "Herein we present a comparison of POLRMT inhibition and ClpP activation, both conceptually and experimentally, and evaluate the results of these treatments on mitochondrial transcription, inhibition of OXPHOS, and ultimately cancer cell growth." (PMID 37371693, 2023). "Hsp60 silencing downregulated ClpP expression, but not vice versa, in multiple other cancer cell types." (PMID 35653190, 2022). "Moreover in other cancers (Jo’s paper), the ONC201 sensitivity of TNBC correlated with the level of ClpP expression." (PMID 34680527, 2021).
cancer (continued). "Only CLPP+/+ and not CLPP−/− cells were sensitive to the imipridones, and ClpP expression levels in cancer cells directly correlated with their sensitivity to the drugs." (PMID 34109219, 2021). "The CLpP protein is overexpressed in many human cancers, including NSCLC regardless of histotype, and is most highly expressed in primary NSCLC lesions that developed metastasis." (PMID 34604049, 2021). "Bacterial ClpP inhibitors, ß-lactones derivatives (A2-32-01) and phenyl ester compounds (TG42, TG53), cross-react with human ClpP and show anti-proliferative and pro-apoptotic effects in human cancer cell lines." (PMID 34888254, 2021). "The tolerability of ClpP loss in mice and humans also raises mechanistic questions as to why inhibiting ClpP is lethal to some cancers, but not normal cells with high ClpP expression." (PMID 33037181, 2020). "To date, the majority of studies in cancer have focused on targeting ClpP and have not extensively investigated ClpX." (PMID 33037181, 2020). "Both ClpP agonists and POLRMT inhibitors inhibit mitochondrial transcription, deplete mtDNA, impair OXPHOS, and are potentially disruptive to multiple aspects of cancer cell metabolism, making them distinct from other mitochondrial targeted approaches (i.e., metformin, CPI-613, etc.)." (PMID 37371693, 2023). "While both ClpP agonists and POLRMT inhibitors show promising anti-cancer properties, there is the potential for the development of resistance, though this may be less likely with ClpP agonists because they effect many pathways including the TCA cycle, protein synthesis, and proline biosynthesis." (PMID 37371693, 2023). "Both ClpP activation or POLRMT inhibition appears to increase glycolytic dependence in cancer cells (become more “Warburg-like”), although it is unclear why shifting cancer cells away from OXPHOS utilization would be therapeutically beneficial given that many cancers are already highly glycolytic." (PMID 37371693, 2023). "ClpP agonists show cytotoxicity in cancer models but not in non-malignant cells." (PMID 37046596, 2023). "Mechanistically, activation of ClpP increases the levels of ATP7A and ATP7B, which are involved in the elimination of cisplatin, and ClpP-mediated cisplatin efflux blocks the production of cisplatin-mtDNA/genomic DNA adducts, thereby inhibiting cancer cell death." (PMID 35180892, 2022). "In human cancer cell lines, efforts to identify CLPP degradation substrates were carried out, using a mitochondrial-matrix-targeted construct for APEX-mediated proximity biotinylation of proteins there, combined with acute knockdown over 48 h of CLPP versus LONP1." (PMID 35954215, 2022). "However, the direct regulators of mammalian ClpP expression, such as transcription factors and epigenetic marks that lead to dysregulated expression in cancer have not yet been fully identified." (PMID 33037181, 2020). "Since high ClpP levels have previously been correlated with poor metastasis-free survival in NSCLC, these SNPs may contribute to a more aggressive disease phenotype by enabling cancer cells to better withstand metabolic and oxidative stress through enhanced mitochondrial proteolysis." (PMID 41155556, 2025). "In addition to emphasizing the importance of mitochondrial transcription in mitochondrial function, elucidating the mechanism of action of ClpP agonists and POLRMT inhibitors could lead to broader discoveries about cancer and how to better treat this prolific disease." (PMID 37371693, 2023).
cancer (continued). "Indeed, numerous preclinical studies have shown that targeting mitochondrial respiration or structure using small molecules can induce cancer cell death, including drugs targeting the ETC, mitochondrial translation, mitochondrial DNA replication, or mitochondrial Protease ClpP." (PMID 34830763, 2021). "Though CLPP has been identified as the target of ONC212, the mechanism of cancer cell death induced by ONC212 is not well-understood." (PMID 39394450, 2024). "An outstanding question is why ClpP agonists and POLRMT inhibitors are effective inhibitors of cancer cell growth, but not normal cell growth." (PMID 37371693, 2023). "Conversely, the silencing of LONP1 and ClpP did not affect the growth of the non-cancerous cell lines BPH-1 and HEK-293, which had lower levels of LONP1 and ClpP than those in cancer cells." (PMID 33637676, 2021). "Furthermore, depletion of LONP1 and ClpP increased cell sensitivity to an SHMT2 inhibitor, suggesting that SHMT2 is a key substrate in the LONP1- and ClpP-mediated proteostasis network and that its protein quality control by mitochondrial proteases may promote cancer cell survival and progression." (PMID 33637676, 2021).